IL6 (interleukin 6)
Diseases named in the same sentence as IL6 in open-access papers (continued):
Sharing a sentence is not in itself a finding about the gene and the disease.
allergic rhinitis (39 papers, 2013 to 2026). Inflammation of the nasal mucous membranes caused by an IgE-mediated response to external allergens. "For example, IL-6 was polymorphic, and it was likely that this polymorphism had a significant impact on allergic rhinitis." (PMID 37634407, 2023). "The result showed that IL-6 rs1800795 polymorphism increased the risk for allergic rhinitis in homozygote comparison (homozygote comparison = 1.74, 95% CI = 1.10, 2.75, p = 0.02)." (PMID 35368692, 2022). "IL-6 and IL-8 are multifunctional cytokines that are implicated in various inflammatory conditions including allergic rhinitis and chronic rhinosinusitis." (PMID 27295300, 2016). "Unlike NP, research findings indicate that possessing the CC genotype of the IL-6 gene (-174G/C) polymorphism may increase the likelihood of developing allergic rhinitis two-fold in the Chinese population." (PMID 38388670, 2024). "This meta-analysis demonstrated that rs1800795 polymorphism of IL-6 gene might be a risk factor for allergic rhinitis." (PMID 35368692, 2022). "Ultimately, the ameliorative effect of dictamnine on allergic rhinitis mice was confirmed through nasal symptom score, serum pharmacodynamic indices (immunoglobulin E (IgE), histamine, IL-2, IL-4, IL-6, and TNF-α), and histopathology." (PMID 40520177, 2025). "The study involved molecular docking analysis of berberine with five key genes (Alb, Il6, Il1b, Tlr4, and Ptgs2) to validate its potential targets against allergic rhinitis." (PMID 38796469, 2024). "In this study, increased nasal secretion of IL-2 and IL-6 was considered anti-inflammatory for allergic rhinitis." (PMID 38707001, 2024). "Il6 plays a crucial role in the development of allergic rhinitis, and its levels escalate as the disease advances." (PMID 38796469, 2024). "Briefly, for each SD increase in peripheral levels of IL-6 and A-FABP, the risk of developing allergic rhinitis decreased by approximately 10%–30%." (PMID 37634407, 2023). "Two case–control studies including 353 patients with allergic rhinitis and 404 controls were utilized to analyze the relationship between IL-6 rs1800795 and allergic rhinitis." (PMID 35368692, 2022). "OVA-sensitized allergic rhinitis mice were orally administered with 4 mg/kg of Rosmarinic acid for 10 days, which led to the degradation of IL-1β, IL-6, TNF-α IL-6, and NF-κB." (PMID 34679659, 2021). "The targets of 48 putative therapeutic components in the treatment of allergic rhinitis include IL6, TNF, CXCL8, ICAM1, ILA, MMP9, IL10, and IL1B." (PMID 31611923, 2019). "The JPSS scores were also positively associated with IL-8 mRNA expression in asthmatic children and IL-6 mRNA expression in children with allergic rhinitis." (PMID 26819847, 2016). "In a study of allergic rhinitis (AR) with OD, our team found that the inhibition of IL-6 in an OD model may improve OD." (PMID 40420944, 2025). "Allergen-specific T helper 2 (Th2) cells and elevated serum IgE are typical manifestations of allergic rhinitis, and the significantly elevated levels of IL-4 and IL-6 also indicate that two cytokines play an important role in the disease process of allergic rhinitis." (PMID 35831673, 2023). "The pathology of allergic rhinitis shows the accumulation and increase of mast cells, dendritic cells, macrophages, etc. in the superficial nasal mucosa, as well as the levels of inflammatory factors such as IL-4, IL-6, IL-8, and IgE were increased." (PMID 35831673, 2023). "Thus, MR can preliminarily confirmed the effect of IL-6 and A-FABP on the risk of allergic rhinitis." (PMID 37634407, 2023). "In addition, it has been suggested that the allergic rhinitis symptoms are alleviated by inhibiting the higher IL-6 expression level, which is a result supporting the pharyngeal allergic inhibitory effect of EAT." (PMID 36012469, 2022).
allergic rhinitis (continued). "Quantitative RT-PCR analysis showed that the expression levels of Il4, a key mediator of Th2 response, and of the Il33 gene, which is necessary for the development of allergic rhinitis, were reduced in the lungs of Mlys-IL-6 KO mice as compared to WT control mice." (PMID 30534125, 2018). "DEP induces expression of IL-6 and IL-8 via p38, Akt, and NF-κB signaling pathways in nasal fibroblasts, suggesting that air pollution might induce or aggravate allergic rhinitis or chronic rhinosinusitis." (PMID 27295300, 2016). "Also, closely related to this issue was the speculation that the effect of IL-6 on allergic rhinitis may be ethnospecific." (PMID 37634407, 2023). "Furthermore, the MCODE plugin was employed to pinpoint 14 genes (Cyba, Nfkbia, Fos, Mpo, Il6, Il1b, Sele, Vcam1, F2, Tlr4, Alb, Egr1, Smad3, and Ptgs2) forming a primary cluster, potentially representing a crucial regulatory network for berberine in treating allergic rhinitis." (PMID 38796469, 2024). "Treatment of allergic rhinitis patients with kaempferol also reduced TNF-α, IL-6, IL-8, IL-1ß, and MIP-3α." (PMID 34552650, 2021). "Supplementation with baicalin in the diet reduced the serum concentrations of IgE, IL-1β, IL-4, IL-6, TNF-α, and histamine in rats with allergic rhinitis, which suggests its potential as a therapeutic agent for allergic rhinitis through inhibition of inflammation mediators." (PMID 41463802, 2025). "Furthermore, berberine (50 or 100 mg/kg) suppressed TNF-α, IL-6, IL-1β, IL-17, and IgE levels in the OVA-induced allergic rhinitis group (p < 0.01)." (PMID 38796469, 2024). "The study provided some interesting, but not sufficient, evidence to suggest that interleukin-6 and adipocyte fatty acid-binding protein might play a protective role in the development of allergic rhinitis at the genetic level." (PMID 37634407, 2023). "α-Pinene, the main component of SO, decreased TNF-α, IL-1β, IL-6, intercellular adhesion molecule-1 (ICAM), and macrophage inflammatory protein-2 (MIP-2) levels, as well as eosinophil and mast cell infiltration in the nasal mucosa in an ovalbumin-sensitized allergic rhinitis mouse model." (PMID 35744988, 2022). "The present study provided some interesting, but not sufficient, evidence to suggest that IL-6 and A-FABP might play a protective role in the development of allergic rhinitis at the genetic level." (PMID 37634407, 2023).
bacterial pneumonia (39 papers, 2011 to 2025). Acute infection of the lung parenchyma caused by bacteria (e.g., Streptococcus pneumoniae, Haemophilus influenzae, Chlamydia pneumoniae, Mycoplasma pneumoniae, and Legionella pneumophila). "Decreased IL‐6 levels (OR, 0.8; 95% CI, 0.66–0.97; p = 0.02) were associated with susceptibility to bacterial pneumonia." (PMID 40501500, 2025). "Our findings that baseline levels of the systemic inflammatory biomarkers hsCRP, IL-6, and d-dimer were associated with subsequent bacterial pneumonia risk are supported by previously published data." (PMID 23457535, 2013). "Furthermore, we tested the diagnostic accuracy of a panel of host response biomarkers for the identification of bacterial pneumonia, among which sTREM-1 and IL-6 displayed excellent diagnostic accuracy." (PMID 34991507, 2022). "The selection of IL-6 and IL-8 was based on their established roles as key mediators in the acute phase response to bacterial pneumonia, providing a focused insight into the immune response." (PMID 41262450, 2025). "In patients with bacterial pneumonia, positive correlations were found between IL-6 and Veillonella parvula (p < 0.001), while TNF-α positively correlated with Capnocytophaga granulosa (p = 0.009)." (PMID 41011430, 2025). "In typical bacterial pneumonia, IL-6 was elevated in MASLD patients at admission (Δ = +2289 pg/mL; 95% CI 95–2283), as was TGF-β1 (Δ = +186 pg/mL; 95% CI 2.7–369)." (PMID 40869413, 2025). "Spearman's rank correlation test revealed that BALF HBP and IL-6 concentrations and N% were lowly correlated with blood HBP and IL-6 concentrations and N% in children with bacterial pneumonia (r = 0.439, P < 0.001; r = 0.250, P = 0.005; r = 0.235, P = 0.008)." (PMID 36910136, 2023). "In the present study, blood HBP and PCT concentrations and N% and BALF HBP and IL-6 concentrations and N% were significantly higher in bacterial pneumonia, and BALF N% was lowly correlated with BALF IL-6 concentrations." (PMID 36910136, 2023). "Blood HBP and PCT concentrations and N% and BALF HBP and IL-6 concentrations and N% were significantly higher in bacterial pneumonia than in viral pneumonia (P < 0.05)." (PMID 36910136, 2023). "In contrast, blood HBP and PCT concentrations and N% and BALF HBP and IL-6 concentrations and N% were significantly higher in the bacterial pneumonia group than in the viral pneumonia group (P < 0.05)." (PMID 36910136, 2023). "It was found that the serum IL-6 level had the highest efficacy for identifying bacterial pneumonia in children." (PMID 34708133, 2021). "Patients with atypical pneumonia related ARDS demonstrated significantly reduced serum levels of IL-6 compared to bacterial pneumonia related or indirect ARDS." (PMID 33673270, 2021). "ARDS by viral pneumonia was characterized by lower serum IL-6 levels than bacterial pneumonia related ARDS." (PMID 33673270, 2021). "To note, the patient with the highest level of IL-6 was the case of confirmed bacterial pneumonia (733 pg/ml)." (PMID 34344349, 2021). "Further, significant, higher IL-6 levels were found in patients with bacterial pneumonia ARDS compared to viral pneumonia related ARDS (p = 0.019)." (PMID 33673270, 2021). "To study the influence of vendor effects on cytokine release in Gram-negative pneumonia, we measured the levels of TNFα and IL-6 in lung homogenates harvested from mice after intranasal infection with K. pneumoniae." (PMID 32840685, 2020). "Regarding inflammatory markers, we focused on IL-6 in combination with PCT because IL-6 plays a well-established role as a key mediator of the acute inflammatory response in bacterial pneumonia and correlates strongly with disease severity and clinical outcomes." (PMID 41262450, 2025).
bacterial pneumonia (continued). "Our study found that UC-MSCs can effectively inhibit the development of bacterial pneumonia, primarily by reducing the number of macrophages and neutrophils and inhibiting the secretion of inflammatory factors IL-1β, IL-6, and TNF-α, thereby suppressing in vivo inflammatory reactions." (PMID 40271073, 2025). "Interestingly, macrophages from the bacterial pneumonia patients have only marginal response scores for IL-6, albeit having higher plasma levels." (PMID 35732153, 2022). "Thus, complications of chickenpox, in particular secondary viral-bacterial pneumonia, can be predicted based on low (less than double-normal) levels of IL-6 and IFN-γ, induced chemiluminescence, CD16, and CD20." (PMID 34795992, 2021). "Our univariate analysis revealed that patients with severe bacterial pneumonia had higher blood HBP and PCT concentrations and N% and BALF HBP and IL-6 concentrations and N%." (PMID 36910136, 2023). "When adjusting for the dilution factor, children with bacterial pneumonia still had higher concentrations of HBP and IL-6 in BALF than children with viral pneumonia (P < 0.001)." (PMID 36910136, 2023). "In the bacterial pneumonia group, HBP and IL-6 concentrations and N% in BALF samples were all significantly higher than those in blood samples (P < 0.001)." (PMID 36910136, 2023). "The age (p < 0.001), hospital stay (p < 0.001), tonsil condition (p < 0.001), interleukin-6 (IL-6; p=0.033), and lactate dehydrogenase (LDH; p < 0.001) between children with bacterial pneumonia and adenovirus pneumonia were significantly different." (PMID 35685584, 2022). "Patients with viral and atypical pneumonia related ARDS possessed significantly lower serum IL-6 levels compared to bacterial pneumonia related ARDS and IL-6 levels in atypical pneumonia related ARDS were significantly lower than in indirect ARDS." (PMID 33673270, 2021). "Because cytokines are important regulators of the inflammatory response to bacterial pneumonia, we measured pulmonary (TNF-α, IL-6, IL-10, CXCL1) and systemic (TNF-α, MCP-1, IL-6, IFN-γ, IL-10, IL12p70) cytokine and chemokine levels." (PMID 26215706, 2014). "On the other hand, it has been shown that IL-6 defective mice have a severely compromised APR to turpentine-induced tissue damage, as well as an impaired response following LPS injection and bacterial pneumonia." (PMID 27301375, 2016). "We hypothesized that biomarkers of pulmonary inflammation would predict the development of bacterial pneumonia better than systemic markers of inflammation, but we found the opposite–hsCRP and IL-6 were related to bacterial pneumonia, but not CC16 or SP-D." (PMID 23457535, 2013). "In bacterial pneumonia, IL-6 concentrations and N% in BALF samples were both significantly higher than those in blood samples, and BALF IL-6 concentrations and N% were lowly correlated with blood IL-6 concentrations and N%, which indicates that the markers in BALF might mirror systemic biomarkers." (PMID 36910136, 2023). "Gram-negative bacteremia, bacterial pneumonia, Kawasaki disease, and active SJIA exhibited similar cytokine profiles with elevated interleukin-6 (IL-6) and/or IL-10, further suggesting a correlation between them." (PMID 37828529, 2023). "IL-6 and TNF were even more robustly induced by the lysate than by Pam2-ODN, but we have shown that they were not required for protection against bacterial pneumonia." (PMID 22299046, 2012). "This would be consistent with other prior observations that interleukin-6 and TNF are both profoundly induced by lysate treatment, but are not required for protection against bacterial pneumonias." (PMID 22299046, 2012).
cystitis (39 papers, 2007 to 2025). Inflammation of the urinary bladder. "In the CYP-induced rat cystitis model, multiplex analysis of cytokine levels also revealed increased inflammation-associated cytokines in the urine and bladder tissue, including IL-6, IL-1β, monocyte chemotactic protein-1, and IL-10." (PMID 24146927, 2013). "A previous study in older patients, also a mix of community based males and females showing susceptibility to rUTIs, identified the urinary markers IL-6 and IL-8, both pro-inflammatory cytokines, to be elevated in bacteriuria, and significantly (4-fold) increased during acute cystitis." (PMID 31338112, 2019). "Since IL6 receptors are expressed on sensory nerves and induce hyperalgesia, suggesting that IL6 is involved in afferent neurotransmission, IL6 in the bladder may act against IL6 receptors on sensory nerves to transmit abnormal urges to urinate which are associated with cystitis." (PMID 37463180, 2023). "ALA can alleviate LPS-induced orchitis and cystitis in mice by inhibiting the activation of the NF-κB signaling pathway, thereby reducing the expression of the inflammatory factors IL-6, TNF-α, and COX-2." (PMID 40427376, 2025). "Urine HBP (UHBP) was found to be significantly superior in the detection of UTIs and in distinguishing cystitis from pyelonephritis, compared to other markers such as IL-6 and WBC, and nitrite in the dipstick test." (PMID 41007875, 2025). "E. coli-induced up-regulation of TNF-α, IL-6, and IL-1β in cystitis rats were reversed by AAV-shTPRG1 injection, demonstrating that TPRG1 contributed to inflammation in E. coli-induced cystitis rat." (PMID 34998360, 2022). "Further investigation is necessary to clarify the role of IL-6 in TH1/TH2/TH17-regulated signaling pathway in ketamine-induced cystitis." (PMID 29204439, 2017). "Further investigation is needed to define the role of IL-6 in TH1/TH2/TH17-regulated signaling pathway in ketamine-induced cystitis." (PMID 29204439, 2017). "We found elevations of serum KC, IL-6, and G-CSF in mice that progressed to chronic cystitis relative to those that resolved infection or were mock-infected with PBS." (PMID 25569799, 2015). "C3H/HeN mice that progress to chronic cystitis upon single inoculation can be predicted by elevated serum levels of IL-5, IL-6, KC, and G-CSF at 24 hpi." (PMID 25569799, 2015). "Bladder infections are typically accompanied by an innate immune response involving vigorous IL-6 and IL-8 production." (PMID 24146927, 2013). "In this study we chose chemokines/cytokines IL-1β, IL-6, IL-8, and TNF-α because they are associated with cystitis and systemic inflammation." (PMID 24098552, 2013). "IL-6 has been used to measure the inflammatory response in the tissues from other cystitis animal models and the increased levels of urinary IL-6 were also reported as a possible biomarker for IC." (PMID 24204996, 2013). "Acute cystitis has been associated with an increase in urine IL-1α, GRO-α, IL-1β, IL-6, IL-8 and TNF-α compared to sterile samples." (PMID 22140570, 2011). "We identified elevated IL-5, IL-6, G-CSF, and KC as a serum biomarker signature prognostic of the development of chronic cystitis in C3H mice." (PMID 20811584, 2010). "The enhanced pro-inflammatory cytokine release in urinary bladder disorders was also reported by previous studies, in which a significant increase in IL-6 levels was measured in the urine of women with interstitial cystitis, in rats with experimentally induced cystitis, and in cats with FIC." (PMID 36851436, 2023). "Since PGE2 and IL6 are released from the bladder epithelium, it may be possible to improve the symptoms of cystitis like IC by suppressing bladder epithelium inflammation and the release of inflammatory molecules." (PMID 37463180, 2023). "Thus, IL6 is produced in the bladder epithelial and stromal layers and is thought to play a role in cystitis development." (PMID 37463180, 2023).